MST1P2 (macrophage stimulating 1 pseudogene 2)
Synonyms: MSPL2; MSPL-2; formerly MSTP2
Gene: Transcribed unprocessed pseudogene on chromosome 1 (16,645,622 to 16,650,289, forward strand). Ensembl gene ENSG00000186301.
Diseases named in the same sentence as MST1P2 in open-access papers:
MST1P2 is named in the same sentence as 4 diseases in open-access papers, as found by Europe PMC text mining. Sharing a sentence is not in itself a finding about the gene and the disease. The quoted sentences say what the papers report.
bladder cancer (1 paper, 2021). "lncRNA MST1P2 (lnc-MST1P2) was confirmed obviously up-regulated in DDP-resistant bladder cancer cells." (PMID 34034626, 2021). "Lnc MST1P2 was also enhanced in cisplatin-resistant bladder cancer cells and regulates the drug-resistance of cells by miR-133b." (PMID 34034626, 2021).
cervical cancer (1 paper, 2021). A primary or metastatic malignant neoplasm involving the cervix. "LncRNA MST1P2 serves as a Cervical Cancer oncogene by sponging with miR-133b." (PMID 34034626, 2021). "Lnc RNA MST1P2 is increased in cervical cancer (CC), but its mechanism in CC has not been clarified." (PMID 34034626, 2021).
cancer (1 paper, 2021). A tumor composed of atypical neoplastic, often pleomorphic cells that invade other tissues. "Further, miR-133b-inhibition significantly attenuate anti-cancer function of si-Lnc MST1P2 both in vitro and in vivo, which verified that Lnc MST1P2 directly targeting miR-133b in CC." (PMID 34034626, 2021). "miR-133b inhibition notably decreased the anti-cancer effect of si-Lnc MST1P2." (PMID 34034626, 2021).
Tumor (1 paper, 2021). "Hela cells was cotransfected with si-Lnc MST1P2 or si-NC and miR-133b-inh or miR-NC, the cells were then used to construct subcutaneous tumor model in nude mice." (PMID 34034626, 2021). "RT-qPCR analysis was carried out on 40 pairs of CC samples and non-tumor tissues to evaluate Lnc MST1P2 expression level." (PMID 34034626, 2021). "In the present study, we shown that Lnc MST1P2 was apparently overexpression in CC tissues as well as cells when comparerd to the paired non-tumor tissues and normal cells." (PMID 34034626, 2021). "It has been proved Lnc MST1P2 making a significant contribution to the development of tumor." (PMID 34034626, 2021). "Lnc MST1P2 expression was significantly up regulated after tumor radiotherapy." (PMID 34034626, 2021). "MiR-133b-inh could obviolusly reverse anti-tumor effect of si-Lnc MST1P2 in vivo, which indicating Lnc MST1P2 promote CC tumorigenicity by suppressing miR-133b." (PMID 34034626, 2021). "Tumor growth in si-Lnc MST1P2 group was notebaly slower than that in si-NC group." (PMID 34034626, 2021). "In the present study, we conducted a series of in vitro and in vivo assays, aimed to explore the molecular mechanism of lncRNA MST1P2 in CC cells and the function in nude mice transplanted tumor, to lay a theoretical foundation for possible clinical application in the future." (PMID 34034626, 2021). "Low expression of Lnc MST1P2 in vivo can inhibit tumor growth in nude mice." (PMID 34034626, 2021).